IL33 (interleukin 33)
Diseases named in the same sentence as IL33 in open-access papers (continued):
Sharing a sentence is not in itself a finding about the gene and the disease.
Achalasia (2 papers, 2022 to 2024). A disorder of esophageal motility characterized by the inability of the lower esophageal sphincter to relax during swallowing and by inadequate or lacking peristalsis in the lower half of the body of the esophagus. "Subsequently, a panel of eleven SNPs in the IL33, IL1RL1, IL23R and IL10 genes was analyzed in an Italian cohort, using TaqMan genotyping assays, reporting significant differences in allele and genotype frequencies of the rs3939286 variant of the IL33 gene between achalasia patients and controls." (PMID 39337632, 2024). "Although our findings suggest an association between CPA3+ mast cells and IL-33 in the esophageal mucosa of achalasia, the lack of significant increase of CPA3 in proximal esophagus also implies a role for IL-33 on other immune cell types in achalasia." (PMID 36450816, 2022).
acute pancreatitis (2 papers, 2013 to 2025). An acute inflammatory process that leads to necrosis of the pancreatic parenchyma. "IL-33, a novel IL-1 cytokine family member, plays a role in various inflammatory conditions but its role in acute pancreatitis is not well understood." (PMID 23418608, 2013). "Future directions of investigation should include studies of the ST2 receptor on acinar cells to better understand the role of IL-33 and its receptor in acute pancreatitis pathogenesis." (PMID 23418608, 2013). "IL-33 stimulates pancreatic acinar cell pro-inflammatory pathways, is induced in stimulated acinar cells and in ligation-induced acute pancreatitis, and exacerbates acute pancreatic inflammation in mice." (PMID 23418608, 2013). "IL-33 is induced in acute pancreatitis, activates acinar cell proinflammatory pathways and exacerbates acute pancreatic inflammation." (PMID 23418608, 2013). "Taken together with our finding of increased IL-33 concentration in the pancreas in ligation-induced acute pancreatitis, we have demonstrated a novel role for IL-33 in the exacerbation of acute pancreatic inflammation." (PMID 23418608, 2013). "We first ascertained expression of IL-33 in our model of ligation-induced acute pancreatitis in mice." (PMID 23418608, 2013). "We have shown that IL-33 is induced in ligation-induced acute pancreatitis in mice and rats." (PMID 23418608, 2013). "We then performed investigations to test the hypothesis that IL-33 exacerbates acute pancreatitis." (PMID 23418608, 2013). "We detected mast cell degranulation in the pancreas and lung in mice and rats with ligation-induced acute pancreatitis, which when taken together with increased IL-33 expression suggests that interactions between IL-33 and mast cells may play a role in disease pathogenesis." (PMID 23418608, 2013). "Exogenous IL-33 induces acute pancreatitis in mice, likely by stimulating acinar cell production of inflammatory mediators, by a mechanism that does not involve mast cell degranulation in the early phase (but may or may not involve mast cell activation without degranulation)." (PMID 23418608, 2013). "The confirmation by other investigators that IL-33 is expressed by human pancreatic acinar cells and that the IL-33 receptor ST2 is increased in the circulation of acute pancreatitis patients emphasizes the potential clinical relevance of our findings." (PMID 23418608, 2013). "According to our proposed scheme, acinar cell stress in early stages of acute pancreatitis produces IL-33 and also other cytokines (e.g., TNF-α, IL-1β) that again stimulate acinar cells to release more IL-33." (PMID 23418608, 2013).
acute sinusitis (2 papers, 2021 to 2023). "These 56 phenotypes include infectious and inflammatory disorders of the upper respiratory tract that were not included in our definition of IURD: acute sinusitis (9p24.1 near IL33 and 17q21.1 near IKZF3) and acute respiratory infections (5q22.1 near TSLP/WDR and 9p24.1 near IL33)." (PMID 36653354, 2023).
adenomyosis (2 papers, 2022 to 2024). The growth of endometrial tissue inside the muscular wall of the uterine corpus. "The results showed that the protein level of IL33 was significantly downregulated in the endometrial tissue of patients with adenomyosis (n=20) compared with the fertile controls (n=20)." (PMID 35937844, 2022). "We found that in the endometria of patients with adenomyosis, both IL33 and HOXA10 expression were lower." (PMID 35937844, 2022). "They demonstrated that the serum IL33 levels were reduced in the adenomyosis, especially in the type of FOC/DIF-ADE." (PMID 35937844, 2022). "A previous study found that serum levels of the cytokine IL33 were decreased in patients with adenomyosis, so we examined the levels of IL33 in the endometria of patients with adenomyosis." (PMID 35937844, 2022). "Patients with adenomyosis have decreased expression of Interleukin-33(IL-33) in their endometrium." (PMID 39886033, 2024). "Only one study investigated the serum IL33 levels in adenomyosis-affected women." (PMID 35937844, 2022). "Few studies have focused on the effect of IL33 on adenomyosis." (PMID 35937844, 2022). "In the present study, we showed that intracellular protein level of IL-33 was downregulated in the endometrium of patients with adenomyosis, and IL-33 expression status was shown to be positively correlated with that of HOXA10, an endometrial receptivity marker." (PMID 35937844, 2022). "In addition, the mean expression of IL33 in normal controls (0.1783 ± 0.025) was higher than that in adenomyosis (0.1415 ± 0.0071), p=0.00182; the mean densities of HOXA10 in the fertile and adenomyosis individuals were 0.3003 ± 0.055 and 0.1878 ± 0.036, p=0.0050." (PMID 35937844, 2022). "Consistently, the positive relationship between IL33 and HOXA10 expression in the endometrium was verified in the analysis of adenomyosis mouse model." (PMID 35937844, 2022). "In our study, we found endometrial IL33 expression was positively correlated to HOXA10 expression and may involve embryo implantation in patients with adenomyosis." (PMID 35937844, 2022).
AIDS (2 papers, 2020 to 2023). A syndrome resulting from the acquired deficiency of cellular immunity caused by the human immunodeficiency virus (HIV). "The IL-1 cytokine family (IL-1α, IL-1β, IL-1Ra, IL-18, IL-36Ra, IL-36α, IL-37, IL-36β, IL-36g, IL-38, IL-33) was defined to be principally responsible for the inflammatory nature of polygenic AIDs." (PMID 33708123, 2020). "IL-33 is activated by the orphan receptor ST2 by affecting multiple pathways such as MAPK and NF-κB to increase the release of inflammatory factors, thereby accelerating the pathogenesis of chronic AIDs." (PMID 37859999, 2023).
alopecia areata (2 papers, 2021 to 2024). Loss of scalp and body hair involving microscopically inflammatory patchy areas. "It found that people with alopecia areata had increased plasma levels of the Type 2 cytokines IL-33, IL-31 and IL-17E (IL-25), in addition to the Type 17 cytokines IL-17A, IL-21, IL-23 and IL-17F." (PMID 38892934, 2024).
auto-inflammatory syndromes (2 papers, 2019 to 2021). "IL-1β, IL-18, and IL-33 were within normal limits or undetectable, and no mutations were found in genes related to the pathogenesis of autoinflammatory syndromes (MEFV, MVK, TNFRSF1A, NLRP3, and NLRP12)." (PMID 34829952, 2021).
basophilic leukemia (2 papers, 2018 to 2023). "A previous study used rat basophilic leukemia MCs, RBL-2H3 to demonstrate that multiple copies of NF-κB and NFAT binding sites were critical in antigen and IL-33 stimulation-driven reporter gene transcription." (PMID 37798647, 2023).
brain inflammation (2 papers, 2018 to 2024). "Therefore, deficiency of IL-33 affected microglial activation and inflammatory cytokine expression in LPS-induced brain inflammation." (PMID 29728120, 2018). "Interleukin-33 (IL-33) was also observed to have enriched in brain lysates of the heat stress group known to exhibit roles in brain inflammation." (PMID 38719902, 2024). "Further, IL-33 derived from astrocytes not only enhanced the inflammatory response of microglia to LPS but also played an essential role in mediating cerebral endothelial activation and subsequent leukocyte recruitment in LPS-induced brain inflammation." (PMID 29728120, 2018). "Our study indicated that IL-33/ST2 signaling plays an important role in the activation of microglia and cerebral endothelial cells and, therefore, is essential in leukocyte recruitment in brain inflammation." (PMID 29728120, 2018).
celiac disease (2 papers, 2020 to 2021). An autoimmune genetic disorder with an unknown pattern of inheritance that primarily affects the digestive tract. "Celiac disease (CD), a chronic immune mediated pathology, is an example of these two functional roles of IL-33, where an exacerbated cytotoxic response against stressed cells is accompanied by an intense but ineffective pro-regulatory response." (PMID 33133101, 2020). "Since these mechanisms can be potentiated in tissues where IL-33 is secreted or released by means of proinflammatory death mechanisms, different IL-33 target cell populations may play a role in the pathogenesis of celiac disease." (PMID 33133101, 2020). "In this work, we aimed to identify the cells expressing molecules associated to IL-33/ST2 axis, to assess the participation of IL-33 alarmin in potentiating local inflammation and evaluate the connection with inflammatory pathways in untreated celiac disease conditions." (PMID 33133101, 2020).
central obesity (2 papers, 2017 to 2018). "In conclusion, the association of the IL-33 rs7044343 polymorphism with both premature CAD and central obesity is established here." (PMID 28045954, 2017). "Since this is the first work that documents the correlation of the IL-33 polymorphisms with premature CAD and central obesity, further studies in an independent group of patients are required to validate the results." (PMID 28045954, 2017). "The results suggest that the IL-33 rs7044343 T allele could be a susceptibility marker for premature CAD and central obesity." (PMID 28045954, 2017).
chronic bronchitis (2 papers, 2023 to 2025). A type of chronic obstructive pulmonary disease characterized by chronic inflammation in the bronchial tree that results in edema, mucus production, obstruction, and reduced airflow to and from the lung alveoli. "Recently, high IL-33 levels were reported to be associated with chronic bronchitis and frequent exacerbation of COPD patients; blockage of the IL-33 and ST2 pathways showed promise in terms of reducing COPD exacerbation." (PMID 36979498, 2023). "A high IL-33 level is associated with a chronic bronchitis phenotype and increased risk of acute exacerbation." (PMID 36979498, 2023). "Chronic Bronchitis Phenotype: Features prominent goblet cell metaplasia with distinct pyroptosis regulation, including IL-33-mediated alternative inflammasome activation that stimulates mucin gene expression." (PMID 41476973, 2025). "Phenotype-specific therapy selection may include NLRP3 inhibitors for frequent exacerbators, AIM2 inhibitors for emphysema-dominant patients, and IL-33 pathway modulators for chronic bronchitis phenotypes." (PMID 41476973, 2025).
clear cell renal carcinoma (2 papers, 2017 to 2018). A malignant epithelial neoplasm of the kidney characterized by the presence of lipid-containing clear cells within a vascular network. "Wang and colleagues analyzed the correlation of prognostic significance and tissue IL-33 expression in patients with clear-cell renal cell carcinoma (ccRCC) after surgical resection and found that IL-33 expression was significantly associated with advanced tumor stage." (PMID 28387719, 2017).
clostridium difficile infection (2 papers, 2019 to 2024). Symptomatic infection due to the spore-forming bacterium clostridium difficile. "During Clostridium difficile infection (CDI), IL-33 activates ILC2 to protect from colonic damage and mortality." (PMID 38376154, 2024).
CMV infection (2 papers, 2017 to 2019). "It was shown recently that IL-33 signals are essential for inflationary expansion of CD8+ TRM in a chronic cytomegalovirus infection." (PMID 31447845, 2019).
coagulation disorders (2 papers, 2019 to 2024). "Whether serum ST2 and IL-33 are associated with pathogen-induced autoantibodies cross-reacting with coagulopathy molecules remains uncertain." (PMID 31877138, 2019).
colorectal adenoma (2 papers, 2022 to 2025). An adenoma that arises from the colon or rectum. "In other cancers, IL‐33 is induced and activated early in the development of colorectal adenomas and regulates the expression of the stemness genes NANOG, NOTCH3, and OCT3/4." (PMID 40860436, 2025).
cutaneous melanoma (2 papers, 2021). A primary melanoma arising from atypical melanocytes in the skin. "We investigated the role of IL-33 in human cutaneous melanoma using TCGA datasets and found that the effects of IL-33 are dependent on the tumor context." (PMID 33621202, 2021). "This study helps us understand the role of IL-33 in cutaneous melanoma and provides possible therapeutic implications of targeting this cytokine." (PMID 33621202, 2021). "We aimed to investigate the role of IL-33 in human cutaneous melanoma." (PMID 33621202, 2021). "In conclusion, we found that IL-33 has a context-specific role in human cutaneous melanoma, which may be determined by the cellular sources of IL-33." (PMID 33621202, 2021).
cyst (2 papers, 2019 to 2020). A sac-like closed membranous structure that may be empty or contain fluid or amorphous material. "We also detected an increased parasite burden in the brains of infected mice that lacked the IL-33 receptor (known as ST2 or il1rl1), by cyst count and quantitative PCR, demonstrating a role for extracellular IL-33 signaling during this infection." (PMID 33108405, 2020).
diabetic cardiomyopathy (2 papers, 2017 to 2025). Diabetic cardiomyopathy is a disorder of the heart muscle in people with diabetes. "Carbon monoxide can reduce cardiomyocyte pyroptosis by inhibiting the IL‐33/ST2L axis in diabetic cardiomyopathy." (PMID 40849678, 2025). "IL‐33/ST2L axis upregulation can induce cardiomyocyte pyroptosis in diabetic cardiomyopathy." (PMID 40849678, 2025). "This study aimed to investigate whether carbon monoxide (CO) can alleviate cardiomyocyte pyroptosis by downregulating the IL‐33/ST2L axis in diabetic cardiomyopathy (DCM)." (PMID 40849678, 2025). "A cardiomyocyte HMGB1/fibroblast TLR4/IL-33 axis contributes to diabetic cardiomyopathy in mice." (PMID 28898270, 2017). "The most formal of an HMGB1/TLR4/IL-33 axis was recently shown in diabetic cardiomyopathy in mice where high glucose mediated cardiomyocyte HMGB1 release interacts with TLR4 on cardiac fibroblasts and results in decrease in IL-33." (PMID 28898270, 2017).
endophthalmitis (2 papers, 2025). An infectious process affecting the internal structures of the eye. "In the endophthalmitis group, there were seven positively correlated cytokine pairs, including IL-6/IL-23 and IL-33/IL12p70, which were positively correlated." (PMID 40563988, 2025). "Despite IL-33’s well-established role in modulating immune responses in inflammatory conditions, its involvement in ocular infections such as endophthalmitis remains largely unexplored." (PMID 40512033, 2025). "To investigate the specific role of IL-33 in endophthalmitis, we used IL-33 KO mice, and our data showed marked differences between bacterial and fungal endophthalmitis." (PMID 40512033, 2025). "First, we assessed IL-33 production in human endophthalmitis by analyzing vitreous samples from patients with confirmed bacterial and fungal etiology." (PMID 40512033, 2025). "Our analysis revealed that IL-33 levels were significantly elevated in all endophthalmitis patients compared to HCs, with relatively higher levels in fungal endophthalmitis cases." (PMID 40512033, 2025). "Building on our findings in human endophthalmitis and experimental models, we next sought to investigate the functional role of IL-33 in the pathogenesis of infectious endophthalmitis." (PMID 40512033, 2025). "In A. fumigatus endophthalmitis, IL-33 levels continue to remain elevated at all time points, where they declined during bacterial endophthalmitis." (PMID 40512033, 2025). "Analysis of patient vitreous samples further confirmed higher levels of IL-33 in bacterial (n=40) and fungal (n=20) endophthalmitis cases." (PMID 40512033, 2025). "Notably, we demonstrated the differential expression and protective function of IL-33 in both experimental models and human endophthalmitis patients, underscoring its potential as a newer therapeutic target." (PMID 40512033, 2025). "Given the emerging role of IL-33 in immunomodulation, particularly in eye diseases (37, –, 39), and its consistent upregulation in experimental bacterial and fungal endophthalmitis, we sought to explore its yet undefined role in endophthalmitis pathogenesis." (PMID 40512033, 2025). "Furthermore, our data show elevated levels of IL-33 in the vitreous of endophthalmitis patients and demonstrate its immunomodulatory role in experimental endophthalmitis." (PMID 40512033, 2025).
endotoxemia (2 papers, 2017 to 2022). "To study whether IL‐33 could alleviate the hyperinflammation caused by PANX1 deficiency during endotoxemia, we pretreated the Panx1−/− → WT mice with recombinant IL‐33 (rIL‐33) 12 h before LPS injection." (PMID 35593197, 2022). "Recombinant IL‐33 treatment rescued LPS‐induced endotoxemia by increasing the numbers of liver‐infiltrating ST2+ Tregs and attenuating the cytokine storm in hepatic PANX1‐deficient mice." (PMID 35593197, 2022). "According to our results, the Panx1−/‐ mice exhibited a more severe cytokine storm during endotoxemia and, in contrast, consistently decreased IL‐33 levels." (PMID 35593197, 2022). "Taken together, these studies show that the IL-33/ST2 pathway is activated during endotoxemia and plays regulatory roles at the level of endotoxin sensing and signaling." (PMID 28168040, 2017). "Furthermore, we showed that hepatic IL‐33 protects against LPS‐induced endotoxemia by increasing liver‐infiltrating ST2+ Treg numbers and promoting the early resolution of excessive inflammation." (PMID 35593197, 2022). "Furthermore, our findings indicated that IL‐33 played a protective role against LPS‐induced endotoxemia through adaptive immunity in addition to innate immunity, which supplemented previous studies." (PMID 35593197, 2022). "In LPS‐induced endotoxemia, hepatic PANX1 controlled IL‐33 synthesis and secretion via the ATP‐P2X7 pathway, thus targeting ST2+ Tregs and promoting the resolution of hyperinflammation." (PMID 35593197, 2022). "In LPS‐induced endotoxemia, since there is no bacterial proliferation, resolution rather than persistent induction of hyperinflammation via IL‐33‐Tregs is vital to protect organs." (PMID 35593197, 2022).
epilepsy (2 papers, 2020 to 2023). A brain disorder characterized by episodes of abnormally increased neuronal discharge resulting in transient episodes of sensory or motor neurological dysfunction, or psychic dysfunction. "Astrocytically-released IL-33 has also been found to drive synaptic engulfment by microglia and microglial activation has been linked to epilepsy in general [see for review of microglia and plasticity]." (PMID 39086689, 2023). "Noteworthily, less is known about the role and underlying mechanisms of IL-33 in the epilepsy model." (PMID 32982679, 2020). "Although IL-33’s roles have become increasingly clear, its precise role and underlying mechanisms in epilepsy have not been elucidated." (PMID 32982679, 2020).
fasciitis (2 papers, 2021 to 2025). Inflammation process in fascia. "We used an air pouch model to examine the effect of the IL-33/ST2 axis on GAS-induced necrotizing fasciitis." (PMID 34638904, 2021). "In this study, we examined the TH2 cytokine, IL-33, on a GAS-induced necrotizing fasciitis model." (PMID 34638904, 2021).